CRP (C-reactive protein)
Diseases named in the same sentence as CRP in open-access papers (continued):
Sharing a sentence is not in itself a finding about the gene and the disease.
Stroke (continued). "Therefore, CRP level measured within 24 h after stroke onset may be independently related to long-term prognosis of ischemic stroke." (PMID 35659067, 2022). "Therefore, some blood-derived proteins, such as TC, LDL-C, Hcy, and CRP, could be potential biomarkers for the diagnosis, prognosis prediction, and progression evaluation of stroke, especially related to brain damage and cognitive impairments." (PMID 35054785, 2022). "Neither inflammation, as evidenced by CRP-levels, nor overall stroke risk (CHA2DS2 VASc score), biomarkers of cardiovascular risk (NT-proBNP, CK) and echocardiographic parameters of atrial remodeling (septal PA TDI, LAVI/a) correlated with FAP concentration in our cohorts." (PMID 36568546, 2022). "Strokes with concomitant malignancy are associated with nonspecific biomarkers such as elevated D-dimer, elevated CRP, elevated fibrinogen, elevated lactate dehydrogenase, low Hb, undetermined stroke etiology (especially ESUS), and multiterritorial infarcts in brain imaging." (PMID 35911907, 2022). "In addition to being a biomarker for inflammation and a proatherosclerotic and prothrombotic factor, CRP may also constitute a predictor of other conditions, such as myocardial infarction, stroke, and sudden death." (PMID 35627363, 2022). "However, it is unclear whether absolute CRP levels and their changes are important, and whether CAR is also associated with the clinical prognosis of neurocritically ill patients with stroke." (PMID 36079002, 2022). "In addition, other inflammatory biomarkers that have been already involved in the pathophysiology of stroke, for example, CRP, metalloproteinases, or interleukins, may be correlated with the poor outcomes of aSAH." (PMID 36016932, 2022). "The assessment of CRP concentration and the number of leukocytes in the blood of the analyzed patients on the first, third and seventh day of stroke may indicate a greater intensity of inflammatory processes in patients with periodontal disease than in other patients." (PMID 35893412, 2022). "Furthermore, the significant reduction in P-selectin response to CRP-XL in the stroke patients seen at day-90 compared to day-0 could also be due to a general downregulation of P-selectin exposure or even shedding from the platelet surface after stroke." (PMID 35041713, 2022). "We therefore aimed to investigate the association of five markers of acute inflammatory—CRP, IL‐6, WBC, neutrophil, and lymphocyte with four poor outcomes defined by overall mortality, NIHSS, mRS, and BI after ischemic stroke in a large retrospective cohort study of stroke patients." (PMID 33314753, 2021). "In addition, in other trials, CRP was also measured after statin usage in stroke patients." (PMID 34489618, 2021). "Noteworthy is that association of these IDO1 variants with stroke is recognizable primarily in groups of patients with advanced age, altered WBC and CRP levels and with particular stroke etiology, all of which could be directly related with altered IDO1 functions." (PMID 34680558, 2021). "Similarly, in the model 2 adjusted for age, sex, hemodialysis, prior stroke, prior myocardial infarction and prior heart failure hospitalization, and model 3 adjusted for age, sex, and levels of hemoglobin, albumin, eGFR and C-reactive protein, both low LBMI and low BF% also predicted mortality." (PMID 34097103, 2021). "Considering the large number of patients and the diagnostic variety among patients without stroke, it might have been more persuasive to explain our negative results for CRP by obtaining diagnostic data other than acute stroke." (PMID 34135849, 2021). "Similarly, increased levels of serum CRP on admission to hospital were associated with cognitive decline one-year post-stroke, independent of the vascular risk profile of the patients." (PMID 34884906, 2021). "Furthermore, homocysteine and hs-CRP levels have also predicted stroke-related mortality." (PMID 33967939, 2021).
Stroke (continued). "Although a crude association between admission CRP level and short-term functional outcome of stroke has been reported, we did not identify an association between the serum CRP and NIHSS in our study, probably because of a relatively high incidence of infection in our patients." (PMID 27682880, 2017). "In addition, sex, NIHSS score, and Hs-CRP were independent predictors for stroke outcome." (PMID 27699084, 2016). "As far as we know this is the first study that has reviewed the early symptomatology of post-stroke pneumonia, investigated the role of CRP as a potential biomarker for early diagnosis (rather than for stroke-associated infections in general), and established a cut-off value for CRP." (PMID 26937636, 2016). "While a cut-off of 25.60mg/L is the optimal value for screening, our findings also show that a CRP value of 64.65 mg/L or above is sufficiently specific to start treatment irrespective of clinical findings while awaiting formal confirmation of post-stroke pneumonia." (PMID 26937636, 2016). "For determination if initial levels (at 6 h) of IL-10, IL-6 and CRP are independently associated with infection in ischemic stroke patients, we performed a binary logistic regression analysis that was adjusted for NIHSS on admission, stroke etiology, and peak levels of S100B." (PMID 25613713, 2015). "Furthermore, white blood cell counts and levels of C-reactive protein, serum/plasma interleukin-6 (IL-6) and tumour necrosis factor-α (TNF-α) are increased in stroke patients; several of these factors have been associated with stroke outcome and recurrence." (PMID 24889329, 2014). "Furthermore PTX3 may reflect the baseline atherosclerotic burden more accurately than CRP particularly under acute stress conditions, such as stroke, because of differences in amino acid sequences and molecular structures." (PMID 24936646, 2014). "The observation that the relation of TIMP-1 to stroke risk was independent of C-reactive protein levels, as well as other cardiovascular risk factors, may indicate that extracellular matrix metabolism is an important process per se." (PMID 21283828, 2011). "This might explain why the association between high CRP and cardioembolism was no more significant after adjusting for confounding factors including stroke severity." (PMID 19400931, 2009). "As continuous variables, IL-6 (p = 0.02), CRP (p = 0.03), MMP-9 (p = 0.004), D-dimer (p < 0.001), LDL (p = 0.03), von Willebrand factor (p = 0.10), and factor VIII activity (p = 0.10) were positively associated with stroke, whereas HDL-3 was inversely associated (p = 0.02) with stroke." (PMID 17571161, 2007). "The C-reactive protein-triglyceride-glucose index (CTI) integrates inflammatory and metabolic parameters but remains unexplored in the context of post-stroke cardiac complications." (PMID 42188065, 2026). "Independent risk factors identified were coronary heart disease (CHD), insular cortex lesions, peak brain natriuretic peptide precursor (peak NT-proBNP), C-reactive protein (CRP), and higher National Institutes of Health Stroke Scale (NIHSS) scores." (PMID 41541883, 2025). "A single measurement of plasma CRP levels can predict future CVD events, such as myocardial infarction (MI) and stroke." (PMID 40842496, 2025). "Research shows a strong correlation between thrombosis, stroke prognosis, and inflammatory markers such as von Willebrand factor (VWF), CD147, CD163, C-reactive protein (CRP), neutrophil extracellular trap (NET), and Actin." (PMID 41036279, 2025). "CRP, measurement of NLR, and interleukin-10 (IL-10) are used as predictors of functional outcomes after stroke." (PMID 40949500, 2025). "Levels of IL-8 (CXCL8) and the acute-phase protein C-reactive protein (CRP) rise slightly later, with CRP peaking at approximately 48 h post-stroke." (PMID 40869247, 2025).
Stroke (continued). "Furthermore, biomarkers like high-sensitivity C-reactive protein (hs-CRP), plasminogen activator inhibitor-1, and lipoprotein-associated phospholipase A2 (Lp-PLA2) have also been studied for their role in the prediction of disease progression and recurrent stroke occurrence." (PMID 40677479, 2025). "The primary aim of this study was to determine a range within which values of body temperature, CRP and WBC are expected in complication-free stroke patients." (PMID 40447994, 2025). "Large prospective cohorts have shown that elevated circulating C-reactive protein (CRP), homocysteine (Hcy) and lactate dehydrogenase (LDH) soon after stroke predict early-onset cognitive decline." (PMID 41268378, 2025). "C-reactive protein (CRP), high-density lipoprotein (HDL) cholesterol, and blood glucose levels were suggested to be potential mediators for stroke, MI, and T2DM, respectively." (PMID 41170532, 2025). "In diabetic individuals, who typically experience accelerated vascular aging and heightened cardiometabolic risk, CRP serves as a sensitive and accessible biomarker that correlates with increased arterial stiffness, plaque instability, and mortality risk, even in the absence of overt MI or stroke." (PMID 40725102, 2025). "Elevated C-reactive protein (CRP) and interleukin 6 (IL-6) levels can signal inflammation, which plays a role in stroke development and progression." (PMID 41296388, 2025). "The positive correlation between the percentage of CD8+ T cells and CRP levels, along with the predominance of CD8+ T cells in patients with HT, one of the most important risk factors of stroke, may indicate their proinflammatory potential in stroke pathogenesis." (PMID 40342517, 2025). "Patients with higher ATRIA scores were more likely to present with severe strokes (NIHSS > 15) independently, even after adjusting for confounding factors such as CRP, EF, and stroke etiology." (PMID 40649038, 2025). "We only found a statistically significant correlation between stroke size measured as NIHSS and CRP in some of the days." (PMID 40447994, 2025). "Physicians should consider a history of headaches, arthritis, and elevated levels of markers of inflammation such as CRP and ESR to be suggestive of a GCA‐related stroke." (PMID 39817601, 2025). "Secondary outcomes included National Institutes of Health Stroke Scale (NIHSS) score, Glasgow Coma Scale (GCS) score, hs-CRP level, adverse events and mortality." (PMID 41088601, 2025). "Body temperature, CRP and WBC were all significantly elevated the first days after stroke, compared to 90-days post stroke." (PMID 40447994, 2025). "Furthermore, high CRP levels may predict the likelihood of future MI and stroke." (PMID 39597855, 2024). "The observed disparities between the two groups were as follows: age (p < .001), outcomes (p < .001), stroke severity (p < .001), TOAST (p < .001), AF (p < .001), Hs‐CRP (p < .001), FBG (p = .024), Hba1c (p = .034), FIB (p < .001), and ALB (p < 0.001)." (PMID 38376013, 2024). "Frail patients have been shown to have elevated inflammatory markers, including C-reactive protein, IL-6, and TNF-α, and elevated levels of Factor VIII and D-dimer, which raise concern for an underlying coagulopathic state which may predispose them to stroke and myocardial infarction." (PMID 38276658, 2024). "Baseline CRP, NLR and baseline glucose was measured with subsequent modified Rankin Scale (mRS) score on day 14 post-stroke." (PMID 38260698, 2024). "The DGMI group showed significant reductions in the National Institutes of Health Stroke Scale (NIHSS) score, modified Rankin Scale (mRS) score, and C-reactive protein (CRP) level, compared to the control group." (PMID 38726464, 2024). "Laboratory investigations showed persistently elevated C-reactive protein (CRP) and erythrocyte sedimentation rate (ESR) levels, which had been raised since the first stroke." (PMID 39544619, 2024).
Stroke (continued). "TMAO manifests opposite effects given that it can directly activate platelets, augmenting the likelihood of thrombosis and stroke as well as increasing the expression of pro-inflammatory cytokines, such as TNF-α, IL-6, and C reactive protein." (PMID 38787240, 2024). "CRP is a significant inflammatory marker that has been shown to be elevated in AIS patients, correlating positively with more severe stroke conditions, higher mortality, and disability rates." (PMID 39238889, 2024). "CRP, mRS at admission, leukocyte count, high-frequency power in HRV, stroke severity at admission, sex, and diastolic BP were identified as the most informative ML features." (PMID 37851190, 2024). "Deep ELC patients also had more severe stroke, higher HDL-C and C-reactive protein levels, and lower baseline diastolic BP, serum triglycerides, and lymphocyte count." (PMID 37324621, 2023). "Multivariate logistic regression analysis revealed that C-reactive protein (CRP), homocysteine (HCY) levels, stroke severity (SS), and the number of stroke lesions (NOS) were independent risk factors for death within 1 year in patients with AIS." (PMID 36908612, 2023). "Combining the results of RF and traditional statistical methods, our model found that D-dimer, CRP, and hemoglobin affected the occurrence of the SHS after stroke in a relatively small sample of data with tightly controlled inclusion criteria." (PMID 37065924, 2023). "Hence, the aim of the current study was to investigate whether or not CRP in the acute stage of stroke is associated with the development of CD." (PMID 37509012, 2023). "Geiger and colleagues performed a comparison of blood nucleosome cfDNA and other potential stroke biomarkers such as neuron-specific enolase (NSE), S100 protein, and C-reactive protein in ischemic stroke patients." (PMID 37212886, 2023). "According to the biological analyses, the cryptogenic stroke group had significantly lower blood levels of glucose, urea, C-reactive protein, AST, and alkaline phosphatase compared with the established-origin stroke control group." (PMID 38247484, 2023). "The levels of homocysteine, cholesterol, triglycerides, low‐density lipoprotein (LDL), d‐dimer, fibrinogen, CRP, NT‐proBNP, HsT, LAD, and LVDd were all higher in the NVAF with stroke group (p < .05)." (PMID 36208092, 2023). "Similarly, tenascin-C is found in the extracellular matrix and is associated with poor prognosis in stroke due to its neuroinflammatory properties, while CRP, a commonly used clinical marker for non-specific general inflammation, did not correlate with futile recanalization." (PMID 38089974, 2023). "Univariate logistics regression analysis showed that right hemisphere, HCY, CRP, NSE, S100β, Anticoagulation, PPI, dysphagia, and SS all had statistically significant correlation with the occurrence of stroke recurrence." (PMID 37051146, 2023). "The relationship between C-reactive protein (CRP) and cognitive decline following a stroke remains controversial and is currently a subject of active research." (PMID 37509012, 2023). "Compared to the non-stroke group, those who developed a stroke were older and had higher BP, FPG, TG, and hs-CRP levels." (PMID 38075971, 2023). "Our assessment of the inflammatory response unveiled a significant and consistent elevation in key inflammatory markers, including NLR, CRP, and ESR, in the Stroke-COVID group." (PMID 38069113, 2023). "The inflammatory response exhibited significant elevation in NLR, CRP, and ESR levels in the Stroke-COVID group, emphasizing the interconnected nature of these physiological responses." (PMID 38069113, 2023). "Although CRP level and CAR were different between stroke subtypes, patterns of ROC curves for predicting in-hospital mortality were similar for the patients with intracranial hemorrhage, the patients with subarachnoid hemorrhage, and total patients." (PMID 36079002, 2022).
Stroke (continued). "Another inflammation marker, the C-reactive protein (CRP)/albumin ratio (CAR), has prognostic significance in inflammatory processes such as cardiovascular diseases and stroke." (PMID 35505647, 2022). "Although the present study provides valuable insights, prospective large-scale studies are needed to further confirm the usefulness of CRP, CAR, and albumin in predicting clinical outcomes of stroke patients with evidence-based conclusions." (PMID 36079002, 2022). "Based on our findings, we suggest the Hcy, CRP, TC, and LDL-C as possible biomarkers in patients with post-stroke cognitive impairment." (PMID 35054785, 2022). "We found lower lymphocyte count, higher C-reactive protein, higher D-dimer, fibrinogen, and LDH levels in patients who had stroke after COVID-19." (PMID 36325667, 2022). "Patients with a history of MI and high serum C-reactive protein (CRP) levels, who received a monoclonal antibody against IL-1β, canakinumab, had a significantly lower incidence of recurrent MI, stroke, or death from CVD compared to patients receiving placebo." (PMID 35563605, 2022). "Highest hazard ratios were observed for CRP, HbA1c and GDF-15, with hazard ratios above 2.4 for MI, and above 1.6 for stroke, when comparing highest to lowest quartile levels of these markers." (PMID 34935094, 2022). "The secondary outcomes are National Institutes of Health Stroke Scale (NIHSS) score, Activity of Daily Living (ADL) Scale score, coagulation function, and serum hypersensitive C-reactive protein." (PMID 35410433, 2022). "The increases in CRP and WBC were observed later, starting on the third and seventh days after the stroke, respectively." (PMID 35330458, 2022). "Herein, we chose C-reactive protein (CRP) as the target biomarker, which can be used to predict fatal cardiovascular disease (CVD) events such as heart attacks and strokes." (PMID 36551130, 2022). "The current study, therefore, investigated the associations between SNPs of inflammatory molecules, consisting of IL-1β, TNF-α, IL-6, IL-10, IL-18, interferon-γ (IFN-γ) and C-reactive protein (CRP), and PSD at 2 weeks after stroke (early-onset PSD)." (PMID 36225923, 2022). "A propensity matched sample from > 3000 Salford Kidney Study (SKS) patients, differentiated by previous stroke at study recruitment, had stored plasma analyzed for interleukin- 6 (IL-6), Von Willebrand Factor (VWF) and C-reactive protein (CRP)." (PMID 35042473, 2022). "In this study, CRP and CAR were more important than CRPc and albumin in predicting mortality of neurocritically ill patients with stroke." (PMID 36079002, 2022). "The same principle applies with regard to stroke severity (NIHSS), some relevant blood results (glucose, cholesterol and C-reactive protein) and severity of comorbidities." (PMID 34406610, 2022). "For haematologic and metabolic indicators, serum levels of CRP, TB, ALB and HCY in patients with stroke (both IS and HS group) were lower than those in the TIA group (all p < .05)." (PMID 35471128, 2022). "Many authors, in addition to evaluating the usefulness of commonly used markers of inflammation, such as suPAR, CRP and WBC, have highlighted the role of T lymphocytes in immune processes in the course of a stroke." (PMID 35330458, 2022). "We investigated the effects of statin therapy on the level of C-reactive protein (CRP) or highly sensitive CRP (hs-CRP), a liver-derived marker of systemic inflammation, among stroke patients." (PMID 34489618, 2021). "Significant increases in stroke patients versus controls were obtained for serum PTX3 (3.14 ± 1.23 vs. 2.44 ± 0.74 ng/ml; p < .001) and C‐reactive protein (CRP – 1.53 ± 0.38 vs. 1.35 ± 0.35 μg/ml; p < .05)." (PMID 33210471, 2021). "CRP was observed to be an independent predictor of SAI, and there was an optimal time window between 24 and 48 h after stroke." (PMID 34092245, 2021).